BRCA2 (BRCA2 DNA repair associated)
Diseases named in the same sentence as BRCA2 in open-access papers (continued):
Sharing a sentence is not in itself a finding about the gene and the disease.
breast cancer (continued). "Two BRCA2 heterozygotes had bilateral synchronous breast cancers." (PMID 32300229, 2020). "About 5–10% of breast cancers are caused by a gene mutation in BRCA1 and BRCA2." (PMID 32824813, 2020). "Furthermore, although we present a large cohort of BRCA2 breast cancer cases, the sample size is still small." (PMID 32333294, 2020). "The high occurrence and death rates of breast cancer in cancer survivors may likely be attributed to BRCA1 and BRCA2 mutations as well as chemotherapy and radiotherapy for prior cancer." (PMID 32250967, 2020). "While BRCA1 carriers predominantly present with high-grade hormone receptor-negative invasive breast cancer, BRCA2 mutation carriers have more luminal breast cancers and a higher proportion of DCIS, sometimes only detected as mammographic calcifications." (PMID 32333294, 2020). "BRCA2 germline mutation related breast cancers on the other hand, do not express any “BRCAness” features except high genomic instability, and express the range of PAM50 phenotypes, similar to all sporadic breast cancers." (PMID 32164626, 2020). "Because breast cancer 1 (Brca1) and breast cancer 2 (Brca2) associates with ovarian aging, we prospectively compared serum AMH concentrations in wt mice, Brca1+/- mice, Brca2+/- mice and Pol β+/- mice at the same age." (PMID 33223510, 2020). "There are two very important breast cancer susceptibility genes, BRCA1 and BRCA2." (PMID 32824581, 2020). "The genetic risk of breast cancer is modelled through estimates of mutations in BRCA1 and BRCA2 genes and an unknown dominant gene." (PMID 32226220, 2020). "Unlike BRCA1 mutation carriers, the pathological feature of breast cancer patients with a BRCA2 mutation is usually similar to sporadic breast cancer." (PMID 33013205, 2020). "Inherited genetic risk factors such as BRCA1 and BRCA2 mutations are observed more often among breast cancer patients, but are not the sole causal factors." (PMID 32731431, 2020). "For example, application of the NCCN version 2.2017 criteria to a cohort of 1371 newly diagnosed breast cancer patients from Norway who were tested for BRCA1 and BRCA2 mutations, revealed that 32 of 38 (88.9%) mutation carriers would have been classified as high-risk." (PMID 31963545, 2020). "Breast cancer was also assessed and the cumulative risk at the age of 80 years was estimated to be 72% (95% CI, 65–79%) for BRCA1 carriers and 69% (95% CI, 61–77%) for BRCA2." (PMID 33086730, 2020). "Our study of 3877 mutation carriers with 426 incident breast cancer cases is the largest prospective cohort to date and the first prospective study investigating breast cancer risk after RRSO for BRCA1 and BRCA2 mutation carriers in the context of menopausal status." (PMID 31948486, 2020). "In many cases breast cancer is caused by mutation in BRCA1 and BRCA2 genes." (PMID 33225921, 2020). "Subsequent large-cohort studies that have used these methods have demonstrated either no statistically significant reduction in breast cancer risk with RRSO or a reduced risk in premenopausal BRCA2 mutation carriers only." (PMID 32337493, 2020). "Interestingly, we also found that the BRCA2 c.7409dup was harbored in two unrelated sporadic breast cancer patients and one hepatocellular carcinoma patient." (PMID 32879886, 2020). "The adverse effect of a positive ER status in BRCA2 carriers with breast cancer may be contingent on exposure to ovarian hormones." (PMID 32939053, 2020). "Currently, both the National Comprehensive Cancer Network (NCCN) guidelines and European Society for Medical Oncology (ESMO) guidelines recommend genetic testing for BRCA1 and BRCA2 for women with multiple primary breast cancers, if first diagnosis was ≤50 years old." (PMID 32854451, 2020). "Currently, there appears to be little justification for complete sequencing of moderate penetrance genes, such as those of ATM, BRIP1, CHEK2, PALB2, and RAD50 in BRCA1/BRCA2-negative high-risk breast cancer families." (PMID 32823908, 2020).
breast cancer (continued). "A total of 302 BRCA1 and BRCA2 negative index breast cancer patients were screened for RECQL germline variants." (PMID 33342430, 2020). "For example, breast cancer risk to age 80 years for BRCA2 carriers with no family history at the 5th and 95th percentiles of the PRS were predicted to be 43% and 67%, respectively, compared with 62% and 85% for those with a family history." (PMID 32665703, 2020). "In addition, genetic testing of breast cancer patients revealed that the population which is of African or Bahaman decent showed higher frequencies of BRCA1 and BRCA2 mutations." (PMID 32824813, 2020). "Many bilateral breast cancer patients with increased hereditary susceptibility to breast cancer result negative for BRCA1 or BRCA2 pathogenic variants and, thus, need a further genetic testing through a broader gene panel." (PMID 32854451, 2020). "When assessed by BRCA1/2 pathogenic germline gene variant, a significant association was observed between weight loss of ≥10 pounds and reduced risk of breast cancer among women with BRCA1 but not BRCA2 pathogenic germline gene variant." (PMID 32165993, 2020). "Moreover, BRCA2 seems to be a good candidate gene to explore in the future given the information available from previous studies in hereditary breast cancer in Uruguay." (PMID 33126731, 2020). "Pregnancy may increase the risk of breast cancer development for BRCA mutation carriers, especially for BRCA2 mutation carriers." (PMID 32070378, 2020). "The absence of BRCA locus-specific loss of heterozygosity in germline BRCA1 and BRCA2 carriers is another potential mechanism of primary resistance, even if the topic is debated and evidences on breast cancer are still lacking." (PMID 32471249, 2020). "The identified breast cancer susceptibility genes in the FA pathway, including BRCA1, BRCA2, BRIP1, PALB2, and RAD51C, are essential genes involved in HR, the error-free pathway for DSB repair during physiological cell cycle progression, which repairs replication-associated DNA damage." (PMID 32300589, 2020). "She underwent BRCA1 and BRCA2 testing because her mother had a history of breast cancer." (PMID 32455662, 2020). "SYCP3 is overexpressed in various human breast cancer cell lines, and EMSY is amplified almost exclusively in sporadic breast and ovarian cancers, suggesting that overexpression of SYCP3 and EMSY phenocopies cancer related-BRCA2 mutations." (PMID 32345962, 2020). "Indeed, for BRCA1 and BRCA2, monoallelic LOF variants present in the germline can result in a nearly tenfold increased lifetime risk of developing breast cancer, whereas bi-allelic LOF variants cause Fanconi anemia (FA)." (PMID 33195396, 2020). "They found that pathogenic CHEK2 variants were the third most frequent germline alterations in both cancers (following BRCA1/BRCA2 variants); however, CHEK2 significantly prevailed in whites over blacks in both breast cancer (2.3% vs. 0.15%) and ovarian cancer (1.3% vs. 0%)." (PMID 33322746, 2020). "The HMMR-BRCA1 interaction influences mammary tumorigenesis as indicated by the association between HMMR polymorphisms and breast cancer risk in carriers of BRCA1 mutations but not BRCA2 mutations." (PMID 32231069, 2020). "It is estimated that a total of 5–10% of all breast cancer cases are genetically susceptible to the disease, with multiple breast cancer susceptibility genes having been proposed, including breast cancer 1 (BRCA1) and breast cancer 2 (BRCA2), two of the major genes." (PMID 32509471, 2020).
breast cancer (continued). "The risk of breast cancer in c.156_157insAlu BRCA2 mutation carriers does not differ from that of other BRCA2 and BRCA1 pathogenic mutation carriers, this is supported by cumulative evidences." (PMID 32070378, 2020). "For BRCA2 mutation carriers, there was statistically significant heterogeneity in the RRSO > 5 years group; this appeared to be driven by a large effect size in GENEPSO, based on only two breast cancers." (PMID 31948486, 2020). "According to a case–control study in 1380 matched pairs of women with BRCA1 and BRCA2 mutations, there is no adverse effect of fertility treatment on the risk for developing breast cancer, compared with controls." (PMID 32070378, 2020). "BRCA1 and BRCA2 breast cancer patients’ fertility were compared to non-BRCA-mutated women with breast cancer and to healthy controls." (PMID 31872386, 2020). "Combined loss of BRCA2‐mediated DNA repair by homologous recombination and RAD52‐mediated single‐strand annealing may result in cell death and reduce breast cancer risk." (PMID 32255263, 2020). "Patients with deleterious mutations in either BRCA1 or BRCA2 have about five times higher risk of breast cancer that those without such mutations." (PMID 33019612, 2020). "The BRCA1 and BRCA2 mutation carriers have a 6–12 times higher lifetime risk of developing breast cancer compared to non-carriers." (PMID 31734900, 2020). "Few clinical and molecular factors have been studied, such as CD133 overexpression and platinum resistance, overexpression of MDR-1 (multi drug resistance 1), having suffered from a previous breast cancer, loss of BRCA function and, presence of mutations in BRCA1 and BRCA2 genes." (PMID 32366278, 2020). "One study of early-onset breast cancer cases and newborn controls in Quebec found that majority of heterozygotes identified harboured a BRCA2 founder variant rather than BRCA123." (PMID 32300229, 2020). "Among these variants, four recurrent variants (BRCA1 c.3257del, BRCA1 c.4801A>T, BRCA1 c.440del, and BRCA2 c.7409dup) might be considered as the candidate locus in breast cancer screening." (PMID 32879886, 2020). "The literature has documented that women who inherited a deleterious BRCA mutation suffer a high lifetime risk of developing breast cancer, with a large-sized prospective study estimating a cumulative incidence of 66 and 61% for BRCA1 and BRCA2 up to the age of 70 years, respectively." (PMID 33505905, 2020). "Nonetheless, the fact that roles other than in HR (i.e., in replication fork stability/recovery) for all three major breast cancer susceptibility genes (BRCA1, BRCA2 and PALB2) have been described, complicates the interpretation of VUS in these genes and their association with cancer risk." (PMID 33195396, 2020). "However, BRCA1 and BRCA2 breast cancers differed in the proportions of patients with ER‐negative disease and basal‐like subtype." (PMID 30175445, 2019). "This may be particularly relevant to the TNBC subtype of breast cancer, which shares similar molecular features to the tumors arising from BRCA1/FANCS and BRCA2/FANCD1-associated DNA repair deregulation." (PMID 30789902, 2019). "This study aimed at identifying inherited pathogenic variants in breast cancer cases from Puerto Rico that were not linked to BRCA1 or BRCA2." (PMID 31780696, 2019). "The association of CASP8 with breast cancer depended on BRCA1/BRCA2 mutation carrier status in some studies, but not others." (PMID 30601841, 2019). "A large sample screening of high-risk breast cancer patients from Hong Kong showed that LGRs accounted for 6.67% (8/120) of all BRCA1/2 pathogenic variants, involving 8.77% (5/57) of BRCA1 and 4.76% (3/63) of BRCA2, respectively." (PMID 31174498, 2019).
breast cancer (continued). "For BRCA2, the highest frequency was observed in families with male breast cancer (14.8%)." (PMID 31528241, 2019). "Collectively, these demonstrated that BRCA1- and BRCA2-deficient breast cancers have different immunophenotype notwithstanding the similar genomic features shared between these groups." (PMID 31022191, 2019). "BRCA2-deficient breast cancers in WSI were enriched for activated CD4 T cells, γδ T cells, type 1 T helper cell, activated B cells, and immature B cell compared to BRCA-proficient breast cancers." (PMID 31022191, 2019). "Thus, risk-stratified breast cancer screening can be enhanced by better classification of variants identified in BRCA1, BRCA2, and other breast cancer genes." (PMID 30832243, 2019). "As expected, BRCA1-, but not BRCA2-, deficient breast cancers were associated with increased T cell-inflamed signature." (PMID 31022191, 2019). "In addition, MAPK12 is associated with breast cancer, while XRCC2 is part of BCDX2 complex, which acts downstream of BRCA2 recruitment and upstream of RAD51 recruitment." (PMID 31870274, 2019). "Given that BRCA1 and BRCA2 are integral in maintaining genomic integrity, we hypothesise that the inactivation of these genes may give rise to breast cancers with such immunogenic phenotype." (PMID 31022191, 2019). "In addition, we demonstrated that the expression levels of BRCA1 and BRCA2 were reduced in breast cancer tissue in comparison to the healthy controls (for both P = 0.0013)." (PMID 30642295, 2019). "In addition to BRCA1 and BRCA2 genes, previous studies supported the contribution of other undetermined genetic factors to the aetiology and prognosis of prostate cancer in breast cancer-prone families." (PMID 31477094, 2019). "However, given the rarity of BRCA2-positive breast cancers (~2% of all breast cancers) it is difficult to construct a large contemporary cohort." (PMID 30723304, 2019). "For BRCA2 mutation carriers, BRRM may lead to similar breast cancer-specific survival as surveillance." (PMID 31302855, 2019). "Nevertheless, the paucity of BRCA2-deficient breast cancers with PTEN mutation in this cohort (n = 1) precluded comparison of T cell-inflamed signature with BRCA2-deficient breast cancers without PTEN mutation." (PMID 31022191, 2019). "In spontaneous breast cancer, the BRCA2 methylation frequencies vary between 0 and 12%." (PMID 31225507, 2019). "Importantly, however, these analyses revealed that PALB2-associated breast cancers with bi-allelic inactivation differ from non-BRCA1/2/PALB2-associated breast cancers but are similar to BRCA1 and BRCA2 breast cancers with bi-allelic inactivation." (PMID 31428676, 2019). "In addition, studies have reported an increased risk of male breast cancer associated with germline mutations in BRCA1, although it represents a lesse frequent association than that with BRCA2 germline mutations." (PMID 31244284, 2019). "However, for men who inherit a PV in a high-risk breast cancer gene, the risk of breast cancer is substantially elevated, with lifetime estimates of 4% for BRCA1 PVs and 7% for BRCA2 PVs." (PMID 30832243, 2019). "The presence of double mutations of BRCA1 and BRCA2 seems to be an extremely rare event in the general population, although not exceptional in Ashkenazi breast-cancer patients." (PMID 31336956, 2019). "No selection was made regarding a woman’s BRCA1/BRCA2 status or other genetic predispositions to breast cancer." (PMID 31491032, 2019). "Besides, a decreased expression of RAD51 was found in low-methylated BRCA2 breast cancer samples (P = 0.022)." (PMID 31506496, 2019).
breast cancer (continued). "For example, 60.13% of the ‘Gene: BRCA1 or BRCA2’ subpopulation had breast cancer before age 50 years, with a mean onset age at 46.80 ± 11.87 years compared to 64% of the ‘Gene: PALB2’ subpopulation that had breast cancer before age 50 years, with a mean onset age at 49.20 ± 8.50 years." (PMID 30759220, 2019). "To this end, we used K14cre;Brca2del/del;p53del/del mouse mammary tumor cells (further denoted as Brca2−/−), together with an isogenic line in which BRCA2 expression was reconstituted using an infectious bacterial artificial chromosome (iBAC) containing the mouse Brca2 gene (denoted as Brca2iBAC)." (PMID 31529615, 2019). "The BRCA2 c.304A>T carrier in this study was diagnosed with breast cancer at the age of 28." (PMID 30968603, 2019). "The results of the comparison of the breast cancer subtypes between the three groups were as follows: triple-negative breast cancer accounted for 89% of the BRCA1 L63X mutation group, 64.4% of other BRCA1 group, and 21.2% of BRCA2 group (p < 0.001)." (PMID 31143373, 2019). "Shortly thereafter, identification and cloning of the breast cancer susceptibility genes 1 and 2 (BRCA1 and BRCA2) took place and led to a marked expansion of our knowledge on genetic susceptibility, its function and impact on tumour biology, and both preventive and therapeutic interventions." (PMID 30915162, 2019). "Our data suggest that BRCA1 testing may be justified for families with multiple female breast cancers, breast and ovarian cancer or early-onset breast cancer and BRCA2 testing for families with male breast cancer from Pakistan." (PMID 31528241, 2019). "In contrast to our study, Antoniou and co-workers found an association of rs4973768 with an increased breast cancer risk in BRCA2 carriers, but we likely did not have enough BRCA2 carriers in our study (n = 11) to find such a link." (PMID 31125336, 2019). "The Tyrer-Cusick model, does not predict the risk of a BRCA1 or BRCA2 mutation, but instead aims to present risk of breast cancer over time." (PMID 30832243, 2019). "LOH towards the mutant allele occurred in ERBB2 and BRCA2 only in the patient metastases of CM01 (including the primary breast cancer), CM02, CM03, and CM08 but not in their corresponding PDCs." (PMID 30700832, 2019). "Taken together, these studies show frequencies of RECQL loss of function variants of 0–2.6% in patients with high-risk familial breast cancer who have previously tested negative for mutations in BRCA1/BRCA2 and other hereditary breast cancer genes." (PMID 30610487, 2019). "BRCA1 and BRCA2 genes are involved in DNA double-strand break repair and related to breast cancer." (PMID 31405066, 2019). "It suggested that aberrant hypermethylation of BRCA2 was associated with its downregulation of expression but also with an overexpression of RAD51, which may lead to AI-resistance and poor prognosis in breast cancer." (PMID 31506496, 2019). "However, pathological high-grade breast cancers and TNBC often showed somatic mutations or abnormal expression of BRCA1 or BRCA2." (PMID 30828495, 2019). "PTEN mutant samples were significantly enriched in BRCA1-, but not BRCA2-, deficient breast cancers compared to BRCA-proficient breast cancers (P = 2.8 x 10−3 and >0.99, respectively)." (PMID 31022191, 2019). "BRCA2-deficient breast cancers displayed similar features of genomic instability as that in BRCA1-deficient breast cancers but did not demonstrate similar immunophenotype as that of BRCA1-deficient breast cancers." (PMID 31022191, 2019).